OR4F15 (olfactory receptor family 4 subfamily F member 15)
Description:
Odorant receptor.
Tractability: Antibody: UniProt places it where antibodies can reach, with medium confidence; UniProt predicts a signal peptide or a membrane-spanning region; its Gene Ontology location is reachable by antibodies, with medium confidence.
Gene: Protein-coding gene on chromosome 15 (101,812,202 to 101,820,197, forward strand). Ensembl gene ENSG00000182854.
Subcellular location: Cell membrane
Pathways (Reactome):
Sensory Perception: Expression and translocation of olfactory receptors
Gene Ontology:
Molecular function: olfactory receptor activity; G protein-coupled receptor activity
Biological process: detection of chemical stimulus involved in sensory perception of smell; G protein-coupled receptor signaling pathway
Cellular component: plasma membrane; membrane
Genetic constraint (gnomAD): Loss-of-function variants: 7 observed, 12.34 expected, observed/expected ratio (o/e) 0.57, 90% interval 0.32 to 1.07. The upper end of that interval is the gene's LOEUF score, 1.07, which puts it in group 4 of 6, group 1 being the genes least tolerant of losing a copy. Missense variants: 443 observed, 394.13 expected, observed/expected ratio (o/e) 1.12, 90% interval 1.04 to 1.22. Synonymous variants: 148 observed, 141.17 expected, observed/expected ratio (o/e) 1.05, 90% interval 0.92 to 1.2.
Homologues: Orthologues: chimpanzee OR4F15 (99% identical), macaque OR4F15 (95% identical), guinea pig OR4F15 (88% identical), mouse Or4f15 (86% identical), rat Or4f15 (84% identical). Paralogues in human: OR4F21 (71% identical), OR4F16 (71% identical), OR4F29 (71% identical), OR4F3 (71% identical), OR4F6 (71% identical), OR4F4 (58% identical), OR4F5 (57% identical), OR4F17 (56% identical), OR4K5 (54% identical), OR4K15 (53% identical), OR4K2 (52% identical), OR4K1 (52% identical), and 116 more.
Diseases named in the same sentence as OR4F15 in open-access papers:
OR4F15 is named in the same sentence as 3 diseases in open-access papers, as found by Europe PMC text mining. Sharing a sentence is not in itself a finding about the gene and the disease. The quoted sentences say what the papers report.
salivary gland carcinoma (1 paper, 2015). A carcinoma that arises from the major or minor salivary glands. "OR4F15 (olfactory receptor, family 4, subfamily F, member 15) have also been found to be associated with salivary gland carcinoma via a GWAS on 309 cases and 535 cancer-free controls." (PMID 26315111, 2015).
OR4F15 also shares sentences with these, for which no sentence is quoted: cancer (1 paper); colorectal cancer (1).